EGFR (epidermal growth factor receptor)
Diseases named in the same sentence as EGFR in open-access papers (continued):
Sharing a sentence is not in itself a finding about the gene and the disease.
tumor (continued). "Cetuximab is a monoclonal antibody that targets the epidermal growth factor receptor (EGFR), which governs several cellular processes pertinent to tumour development and progression." (PMID 17242694, 2007). "Immunohistochemical analyses of these tumors have shown that the tumor cells frequently express KRT5/6, EGFR and KIT." (PMID 17910759, 2007). "Increases in EGFR copy number, defined as an EGFR/CEP7 ratio ≥ 2.0, were observed in ten of twenty-six tumours." (PMID 17626639, 2007). "Consequently, the use of anti-EGFR treatment with monoclonal antibodies could be at least theoretically inappropriate in these tumours, whereas the use of a treatment strategy including TKIs that can interfere with the EGFR downstream pathway could be more appealing." (PMID 17579627, 2007). "Addition of assessment of serum HER2 and serum EGFR to CEA and CA15.3 into a 'tumour marker profile' significantly increases the chances that one of these markers will be raised (52% to 78%)." (PMID 17976236, 2007). "We therefore studied tumour specimens from 54 patients with CUP enrolled in one of a large prospective randomised phase II trial to determine EGFR, Her-2/neu, and c-Kit protein expression." (PMID 17876336, 2007). "EGFR expression and tumour response to a novel preoperative radiation protocol, namely HDREB, was evaluated on whole tumour biopsy specimens." (PMID 17311026, 2007). "The in vivo response of PTHrP gene expression to treatment with an EGFR TKI was evaluated by measuring plasma PTHrP concentrations and PTHrP mRNA from tumours in hypercalcaemic mice with RWGT2 xenografts." (PMID 17533397, 2007). "Correlative studies showed a reduction in phosphorylated EGFR and ERK in tumour tissue post-treatment." (PMID 16570047, 2006). "In contrast, when neoplastic cells in another region of the same tumor had nuclear FABP7 immunoreactivity, the EGFR immunoreactivity was usually prominent." (PMID 16623952, 2006). "We found that if a cluster of tumor cells had only cytoplasmic FABP7 immunoreactivity, the EGFR staining was minimal." (PMID 16623952, 2006). "Transcriptional targets of nuclear EGFR and HER-2, those identified thus far, are closely involved in tumorigenesis, and tumour proliferation and progression." (PMID 16434982, 2006). "It has been previously reported that EGFR signaling induces FABP7 expression in a Ras-independent pathway in normal and tumor Schwann cells, providing evidence of possible interaction between these two proteins." (PMID 16623952, 2006). "In the heterogeneous specimens, the ratio EGFR to CEP 7 can be significantly impacted by the selection of cells to be scored, thus sustaining the proposed scoring in multiple tumor areas as an attempt to obtain a more representative result." (PMID 16911776, 2006). "Consequently, a recurrent tumor may tend to include less EGFR-positive cells." (PMID 17163999, 2006). "All 16 skin specimens only demonstrated the presence of EGFR homodimers and it is unlikely that the HER receptor dimer distribution would be identical in all 16 tumours." (PMID 16306877, 2006). "Preclinical studies showed that anti-EGFR antibodies enhanced anti-tumor effects of irradiation, suggesting that combining immunotherapy to radiotherapy and chemotherapy may be successful in anti-tumor therapies for cancers exhibiting EGFR nuclear localization." (PMID 17049074, 2006). "Preliminary data on microarray and immunoblot demonstrate a potential relationship between EGFR/STAT3 signalling pathway and the expression of ena/VASP and caspase 3, which related to cell motility and apoptosis, both key processes in tumour progression." (PMID 16804520, 2006). "Four tumours with increased LRIG1 copy number were analysed by RT-PCR for EGFR/ERBB1, and all four showed significantly lower expression of EGFR/ERBB1 and three showed significantly higher expression of ERBB2 than their matched normal controls." (PMID 16168117, 2005).
tumor (continued). "Instead, there was a good correlation between EGFR expression (or EGF-induced JNK activation) and drug resistance among ovarian and germline tumour cells." (PMID 15655552, 2005). "Three genes in this pathway had IRs >2 in our set of 47 primary tumors; EGFR in two tumors, ERBB2 in three tumors, and GRB2 in one tumor." (PMID 16457699, 2005). "A wide variety of human tumours including breast, NSCLC, bladder and SCC of the head and neck have been reported as expressing moderate to high levels of EGFR." (PMID 15611794, 2005). "It was postulated that some tumours may produce high levels of EGFR ligands (TGF-α, EGF), thus stimulating EGFR expression in tumour-associated endothelial cells and setting up a paracrine endothelial cell survival signalling pathway that is sensitive to inhibitors of EGFR signalling." (PMID 15928657, 2005). "We reported that HB-EGF is involved in EGFR signal transactivation induced by LPA in OVCA cell lines, and that the soluble form of HB-EGF is attributable to tumour growth on xenografted mice using OVCA cell lines." (PMID 15827558, 2005). "The EGFR autocrine signalling pathway is central to cancer progression, and overexpression of EGFR and/or its ligands, transforming growth factor (TGF)-α and EGF has been reported in many human tumours." (PMID 15928657, 2005). "Patients with tumours positive for both EGFR and HER3 had similar outcome than patients EGFR FISH+/HER3− (OR=36.4 vs 29.4%, P=1.0; DCR=63.6 vs 58.8%, P=1.0; TTP=7.7 vs 9.0 months, P=0.32, and OS=13.8 vs 18.7 months, P=0.85)." (PMID 16288303, 2005). "LRIG1 has been proposed to interact with and counteract the effects of growth factor receptors such as EGFR/ERBB1, thereby functioning as a tumour suppressor." (PMID 16168117, 2005). "In addition to complementing chemotherapy regimens, it is possible that targeted agents could enhance the therapeutic efficacy of radiation therapy as VEGF levels and tumour cell EGFR expression have been shown to increase following exposure to ionising radiation." (PMID 15928655, 2005). "For example, an analysis of trial outcomes according to HER1 (EGFR) and HER2 (ErbB2) status demonstrated that the difference in the effectiveness of letrozole and tamoxifen was particularly marked for tumours that coexpressed ER and HER1 and/or HER2." (PMID 14710200, 2004). "In vitro experiments demonstrate that EGF stimulation of EGFR-positive NSCLC cell lines can result in the upregulation of MMP-9 and, likewise, inhibition of EGFR in vivo reduces tumour cell MMP-9 expression." (PMID 15365565, 2004). "However, another study using human tumour xenografts found that gefitinib caused growth inhibition of tumours and enhancement of the activity of a number of cytotoxic drugs, but neither was dependent on high levels of EGFR expression." (PMID 15560844, 2004). "Furthermore, the activation of downstream effectors of the EGFR signalling pathway have been shown to increase cellular resistance to ionizing radiation, suggesting that EGFR inhibitors may lead to a reduction in tumour cell repopulation and the modulation of cellular radiosensitivity." (PMID 15150574, 2004). "It has also been revealed that EGFR and HER-2 can potentiate tumour cell adhesion to endothelial cells, by enhancing the synthesis of hypoxia-inducible factor (HIF)-1α, and/or carbonic anhydrase-9 through a PI3 kinase-dependent pathway." (PMID 14710236, 2004). "The ratio between EGFR and LRIG1 was more than 2.5-fold higher in the eight tumours compared with matched uninvolved kidney cortex and was at least two-fold higher than the mean normal ratio in 21 of 31 samples analysed." (PMID 14520461, 2003). "In order to examine the mRNA expression of EGFR and LRIG1 in RCC, 31 tumour RNA samples and corresponding kidney tissue in eight of these patients were analysed by quantitative RT–PCR." (PMID 14520461, 2003).
tumor (continued). "Our results suggest that EGFR and TFR are widely distributed on SCCs, especially on proliferating cells at the invading tumour margin." (PMID 2372483, 1990). "As expected the PPEA-polyplex does not activate the EGFR kinase, but kills tumor cells expressing medium to high levels of EGFR." (PMID 42085373, 2026). "Our findings demonstrate that EGFR-mutant SCLC is composed of mixed cell states with distinct therapeutic vulnerabilities and offer a therapeutic strategy to target tumor heterogeneity in highly plastic and treatment-resistant malignancies such as transformed SCLC." (PMID 41574603, 2026). "Increasing evidence indicates that oncogenic drivers, including EGFR, ALK, KRAS, MET, RET, and BRAF, actively shape the tumor immune microenvironment (TIME) by regulating antigen presentation, immune cell infiltration, cytokine signaling, metabolic programs, and immune checkpoint expression." (PMID 42079655, 2026). "Other circulating miRNAs upregulated in ESCC include miR-25, which supports tumor progression by repressing several tumor-suppressor genes and activating the TGF-β, VEGFA/VEGFR, EGF/EGFR, and Wnt/β-catenin signaling pathways, which are fundamental for angiogenesis and metastasis." (PMID 41596525, 2026). "Furthermore, a positive correlation between the classifier and EGFR expression was found in the two patient cohorts consisting of both HPV-positive and HPV-negative tumours." (PMID 41281627, 2026). "Combined CDK9 and EGFR inhibition disrupted transcriptional programs, enhanced TNBC cell death in vitro, and acted synergistically to reduce tumour growth in PDX and Hs578T xenograft models, although this combination was also associated with increased toxicity." (PMID 41505030, 2026). "Anti-EGFR strategies employ a range of ligands, including monoclonal antibodies such as cetuximab, peptides like GE11 and its analogues, and nucleic acid aptamers, all of which enhance tumor-specific accumulation and internalization of drug-loaded carriers." (PMID 41489768, 2026). "Recent studies further demonstrate that KRAS-G12C inhibition leads to heterogeneous cellular responses, with subsets of tumor cells escaping via rapid re-synthesis of active, drug-insensitive KRAS protein, maintained through EGFR and Aurora kinase (AURK) signaling." (PMID 41526435, 2026). "Importantly, EGFR directly phosphorylates ERK1/2 at threonine (T) 202 / tyrosine (Y) 204 and activates ERK1/2, thereby promoting tumor cell proliferation and tumor growth in vivo." (PMID 41565660, 2026). "Furthermore, numerous immune-tumor interaction pathways (e.g., MAPK, PI3K/Akt/mTOR, ErbB/EGFR) varied between MBM and ECM." (PMID 40954493, 2025). "This is in line with previous findings for EGFR-targeting diabody-scTRAIL fusion proteins (Db-scTRAIL) and dimeric EHD2-scTRAIL fusion proteins, all exhibiting very strong tumor cell killing activity with subnanomolar EC50values, although different pharmacokinetic properties." (PMID 40328809, 2025). "Additional studies demonstrated that Olig2 deletion reduces tumor growth and drives a phenotypic shift from oligodendroglial to astrocytic features, concomitant with PDGFRA downregulation and compensatory EGFR signaling pathway activation, revealing alternative routes for tumor recurrence." (PMID 40428395, 2025). "Here, we show that glycine decarboxylase (GLDC), a key enzyme in glycine metabolism, functions as an inhibitor of MHC-I expression in EGFR-activated tumor cells to induce immune escape by a mechanism independent of its enzymatic activity." (PMID 40926122, 2025). "In various tumor cell lines, endogenous RHBDL2 activity has been observed, where it cleaves EGF just outside its transmembrane domain, promoting its secretion and triggering EGFR activation." (PMID 40668798, 2025).
tumor (continued). "Importantly, EVs carry tumour-specific molecules (mutant EGFR, KRAS, PD-L1, oncogenic miRNAs, etc.)that reflect the molecular status of the tumour." (PMID 41311647, 2025). "EGFR again, provides much promise as a potential target, with preclinical HNSCC models demonstrating that radiolabelled Panitumumab and Cetuximab—both anti-EGFR monoclonal antibodies—exhibited good tumor targeting efficacy with some tumor growth inhibition." (PMID 40868227, 2025). "Moreover, MIG-6 overexpression increased EGFR/AKT signaling and promoted tumor proliferation and metastasis of GC cells in vitro." (PMID 40535815, 2025). "Targeting metabolic reprogramming via the EGFR/AKT and mevalonate pathways or modifying cholesterol and fatty acid synthesis, in conjunction with leveraging oxidative stress-induced DNA damage in tumor cells, presents alternative strategies to hinder the progression of GBM." (PMID 40867215, 2025). "Interestingly, when we analyzed the tumors from mice grafted with a 1:1 mixture of the labelled EGFR-low/high cells, the EGFR-low cells were residing in the edges of the tumor, suggesting that they might be responsible for forming the invasive or protective front on the edge of the tumor." (PMID 39747003, 2025). "Importantly, the inhibition of both EGFR and MET receptors resulted in tumor blockage and even regression, highlighting the therapeutic relevance of dual inhibition." (PMID 40725428, 2025). "Our results suggest a prognostic role of IDO-1 protein expression in NSCLC tumor and immune cells independent of EGFR, KRAS AND PD-L1 expression, and should be explored as a predictive biomarker in clinical studies with IDO-1 targeted therapies." (PMID 40475772, 2025). "Taken together, these results indicate that PLCH1 is closely linked to the activation of key oncogenic pathways, including EGFR-MAPK signaling, cell cycle regulation, and DNA repair processes, all of which play vital roles in tumor progression and genomic stability." (PMID 40519297, 2025). "Moreover, a low dose of warfarin below the anticoagulant dosage, effectively blocks γ‐carboxylation of the Gla domain of PRRG1, reverses its regulation on KRAS and EGFR, and PDAC in vivo tumour growth." (PMID 39843398, 2025). "These preclinical findings provide evidence that EGFR-targeted CAR-T therapy could be a promising strategy for treating HNSCC, offering targeted tumor destruction while minimizing collateral damage to healthy tissue." (PMID 40312353, 2025). "Given its role in promoting aggressive tumor fates or therapy resistance, our findings suggest that targeting EZH2 may be a viable strategy to combat EGFR-TKI resistance." (PMID 40414926, 2025). "Given the role of EGFR mutants and overexpression in enhancing immune‐suppressive mechanisms, various cytokines secreted by the tumor cells promote a TME that is not supportive of immune effector cell function." (PMID 40859900, 2025). "Overexpression of EGFR plays a key role in HNSCC, supporting the use of cetuximab, a monoclonal anti‐EGFR antibody, as well as EGFR‐tyrosine kinase inhibitors (EGFR‐TKI), which inhibit tumor cell proliferation and the secretion of pro‐angiogenic factors by tumor cells, such as VEGF and IL‐8." (PMID 40766966, 2025). "used scRNA‐seq to construct a lineage map of resistance to anti‐EGFR therapy in triple‐negative breast cancer, which successfully revealed the dynamic changes in tumor clones and mechanisms of tumor resistance." (PMID 40491322, 2025). "Notably, in EGFR-mutant LUAD, GREM1 overexpression perpetuates PI3K/AKT/mTOR pathway activation, sustaining tumor cell survival and proliferation, which consequently attenuates the efficacy of EGFR-TKIs such as osimertinib." (PMID 41048340, 2025).
tumor (continued). "With in vitro experiments, in vivo subcutaneous tumor, and a transgenic autochthonous tumor model, it is revealed that Plac1 expression promotes HNSCC progression by inducing epidermal growth factor receptor endocytosis and recycling to increase PI3K/AKT signaling pathway activity." (PMID 40056047, 2025). "In addition, there are strong selective genes such as TDGF1, EGFR, and FLT3, whose downregulation can also inhibit tumor growth." (PMID 40046734, 2025). "•Innovative immunotherapies, such as CAR T cell therapies targeting GD2 and EGFR, NK cell-based treatments, and TCR-transduced T cells, are under active investigation, representing cutting-edge approaches to enhance immune-mediated tumor control in EwS." (PMID 40242222, 2025). "Furthermore, it has been found that tumor cell lines with a high EMT score are, interestingly, responsive to PDGFR inhibitors yet resistant to EGFR inhibitors." (PMID 40076457, 2025). "Also in vivo, in the subcutaneous TNC+ EGFR+ MDA-MB-231 xenograft model, significantly enhanced control of tumor growth was observed after injection of CIK cells transfected with dual, compared to single constructs." (PMID 40944718, 2025). "Baseline molecular profiling was often mandatory in patients with non-squamous histology to exclude tumours that harbored an alteration in EGFR or ALK genes, while other more rare molecular alterations were not mentioned in the eligibility criteria." (PMID 40628491, 2025). "The binding of EUDAL to EGFR prevents its ubiquitination and degradation, facilitates its sustained phosphorylation, and subsequently activates downstream STAT3 signaling, which leads to autophagy-related drug resistance in tumor cells." (PMID 40940319, 2025). "Anti-CD3 x anti-EGFR bispecific antibody-armed activated T-cells (AATC) attach and selectively cross-link EGFR-expressing tumor cells and CD3-expressing T-cells, resulting in cytotoxic T-lymphocytes (CTLs) activation and selective cytotoxicity towards the EGFR-expressing tumor cells." (PMID 40407689, 2025). "However, our prior work showed that CD24 is essential for tumor growth and metastatic progression in human TNBC cells, as it promotes oncogenic signaling via EGFR and MET." (PMID 40783744, 2025). "ELK1 was found to be crucial in successful EGFR signaling, and the study also reported a positive correlation of ELK1’s and MCL1’s expression levels in BC tumors, further reinforcing the TF’s role in tumor progression and aggressiveness." (PMID 40862737, 2025). "We show an undescribed HELDR-KAT7 axis that enhances GBM tumor malignancy independent of EGFR signaling." (PMID 40678238, 2025). "In addition, M2 macrophages decreased the anti-tumor effects of vinorelbine by upregulating p-STAT3 and p-EGFR and downregulating BAX." (PMID 40076874, 2025). "A previous study of the anti-EGFR Nanofitin showed high tumor specificity in vivo, with significant accumulation in EGFR-expressing tumors and minimal accumulation in non-EGFR-expressing tumors or healthy organs (heart, lungs, skin) 2.5 h post-injection." (PMID 40305184, 2025). "The classical subtype is defined by epidermal growth factor receptor (EGFR) amplification, loss of PTEN, and mutations in cyclin-dependent kinase inhibitor 2A (CDKN2A), all of which contribute to aggressive tumor behavior and a negative prognosis." (PMID 40075663, 2025). "VEGF can promote tumor growth by activating PI3K/AKT and MAPK pathways independently of EGFR." (PMID 40961974, 2025). "The scope of targeted tumor cells primarily encompasses hematological malignancies (including B-cell malignancies targeted by CD19) and solid tumors (such as epidermal growth factor receptor [EGFR] or programmed cell death ligand 1[PD-L1]-positive tumors)." (PMID 41181137, 2025). "Consequently, the present study focused on the molecular characterization of the functional link between EGFR-mediated EMT and tumor cell dissemination as a starting point to derive EGFR-entailed phenotypes predicting Cetuximab response." (PMID 40121428, 2025).